SYNM (synemin)
Description:
Type-VI intermediate filament (IF) which plays an important cytoskeletal role within the muscle cell cytoskeleton. It forms heteromeric IFs with desmin and/or vimentin, and via its interaction with cytoskeletal proteins alpha-dystrobrevin, dystrophin, talin-1, utrophin and vinculin, is able to link these heteromeric IFs to adherens-type junctions, such as to the costameres, neuromuscular junctions, and myotendinous junctions within striated muscle cells.
Synonyms: DMN; KIAA0353; SYN
Tractability: Antibody: its Gene Ontology location is reachable by antibodies, with medium confidence. PROTAC: ubiquitination databases record sites on it; its protein half-life has been measured.
Gene: Protein-coding gene on chromosome 15 (99,098,217 to 99,135,593, forward strand). Ensembl gene ENSG00000182253.
Subcellular location: Cytoplasm, cytoskeleton; Cell junction, adherens junction
Subcellular location (Human Protein Atlas): Intermediate filaments
Gene Ontology:
Molecular function: protein binding; structural constituent of cytoskeleton; structural constituent of muscle; vinculin binding; intermediate filament binding
Biological process: fast-twitch skeletal muscle fiber contraction; intermediate filament cytoskeleton organization
Cellular component: costamere; intermediate filament; intermediate filament cytoskeleton; neurofilament cytoskeleton; sarcolemma; adherens junction; cytoskeleton; membrane
Genetic constraint (gnomAD): Loss-of-function variants: 88 observed, 89.16 expected, observed/expected ratio (o/e) 0.99, 90% interval 0.83 to 1.18. The upper end of that interval is the gene's LOEUF score, 1.18, which puts it in group 5 of 6, group 1 being the genes least tolerant of losing a copy. Missense variants: 2,069 observed, 1,936.8 expected, observed/expected ratio (o/e) 1.07, 90% interval 1.03 to 1.11. Synonymous variants: 877 observed, 795.87 expected, observed/expected ratio (o/e) 1.1, 90% interval 1.04 to 1.16.
Homologues: Orthologues: chimpanzee SYNM (98% identical), macaque SYNM (94% identical), mouse Synm (69% identical), rat Synm (69% identical), guinea pig SYNM (59% identical), dog SYNM (41% identical), tropical clawed frog synm (29% identical), zebrafish synm (18% identical). Paralogues in human: KRT5 (9% identical), KRT75 (9% identical), KRT6A (9% identical), KRT6C (9% identical), KRT2 (9% identical), KRT6B (9% identical), KRT8 (9% identical), KRT79 (9% identical), KRT1 (8% identical), KRT4 (8% identical), KRT71 (8% identical), KRT73 (8% identical), and 56 more.
Diseases named in the same sentence as SYNM in open-access papers:
SYNM is named in the same sentence as 28 diseases in open-access papers, as found by Europe PMC text mining. Sharing a sentence is not in itself a finding about the gene and the disease. The quoted sentences say what the papers report.
astrocytoma (6 papers, 2010 to 2021). "Synemin is associated with migration in astrocytoma via interactions with the focal adhesion associated protein zyxin and regulation of actin dynamics." (PMID 31003495, 2019). "In astrocytoma cells, high migration potential was correlated with the presence of another IF, i.e., synemin, at the leading edge; when synemin was downregulated, cell migration slowed down." (PMID 34572001, 2021). "In astrocytoma cells, synemin regulates Akt phosphorylation by interacting with PP2A to regulate proliferation." (PMID 32670437, 2020). "Synemin is co-localized with the actin cross-linker α-actinin at the cell front and down-regulation of synemin impaired astrocytoma motility, via reduced F-actin and α-actinin amounts." (PMID 31003495, 2019). "The intermediate filament synemin seems to be an additional part of the motile machinery of astrocytoma cells." (PMID 31003495, 2019). "Similarly enigmatic to plectin–nestin interactions in astrocytes are interactions of plectin with synemin, which is expressed in astrocytomas as well as immature and reactive astrocytes, where it incorporates into vimentin filaments and associates with GFAP." (PMID 34572001, 2021). "In astrocytoma cells, synemin enriches the membrane domains involved in cell movement." (PMID 32670437, 2020). "Nevertheless, synemin’s presence in the ruffled parts of the plasmalemma of human astrocytoma cells, which are rich in α-actinin, opens the possibility that, in tumors, synemin may interact with cell membranes and possibly play a role in cell motility." (PMID 32630739, 2020). "Synemin is expressed in astrocytoma cells, but not in mature astrocytes." (PMID 32670437, 2020).
breast carcinoma (5 papers, 2017 to 2022). "Reportedly, the silencing of synemin results in the suppression of tumor proliferation, whereas its hypomethylation is associated with aggressiveness in breast cancer." (PMID 35361267, 2022). "Synemin is a feasible tumor suppressor, and its promoter methylation status can predict the risk of recurrence in patients with breast cancer." (PMID 32670437, 2020). "SYNM is a type IV intermediate filament involved in the modulation of cell adhesion and motility; in breast cancer, SYNM methylation is associated with shorter recurrence-free survival." (PMID 28927421, 2017). "In breast cancer, synemin expression is modified by aberrant promoter methylation and correlates with early relapse." (PMID 32605308, 2020). "In normal breast epithelial cells, the expression level of synemin increases due to the methylation of the promoter of the synemin gene but drastically decreases in breast cancer." (PMID 32670437, 2020).
glioblastoma (5 papers, 2012 to 2020). The most malignant astrocytic tumor (WHO grade IV). "In human glioblastoma cell lines synemin co-localized with α-actinin at ruffled membranes, which are cellular domains active in cell motility." (PMID 32258037, 2020). "Reducing synemin in glioblastoma cell lines led to decreased phosphorylation of Akt and Rb and an increase in protein levels of p21Cip1 and p27Kip1." (PMID 32258037, 2020). "It is re-expressed in these cells, however, under pathophysiological conditions, in reactive astrocytes and glioblastoma tumors as discussed in the section Changes in Synemin Expression: Astrocytes." (PMID 32258037, 2020). "RNAi experiments in multiple human glioblastoma cell lines revealed synemin enhances the migratory properties of astrocytoma cells and plays a role in enhancing glioblastoma cell proliferation through its effects on the PI3K-Akt signaling pathway." (PMID 32258037, 2020). "The increase in Akt phosphorylation in skeletal muscle in synemin null mice is in contrast to the reduction seen in glioblastoma cell lines treated with synemin shRNA." (PMID 32258037, 2020). "Similar results implying a role of synemin in a cell self-maintenance/differentiation balance were obtained for muscle satellite cells and glioblastoma cells." (PMID 29963074, 2018). "In glioblastoma, synemin controls cell proliferation through AKT by antagonizing PP2A." (PMID 32605308, 2020). "Synemin was shown to have a role in glioblastoma cell proliferation due to its ability to bind PP2A and sequester it away from Akt and may have a similar role in these pathologies." (PMID 32258037, 2020). "Synemin localized in non-junctional membrane was shown to co-localize with desmin and α-actinin in neonatal cardiac myocytes and U-373 MG cells (human glioblastoma cells), respectively." (PMID 32258037, 2020).
cardiomyopathy (3 papers, 2021 to 2022). A disease of the heart muscle or myocardium proper. "While none of these specific variants have been described as pathogenic, PRDM16, SYNM and TTN are well-known cardiomyopathy-associated genes." (PMID 35260914, 2022). "Other studies focusing on a Han population found an association between a prognosis of heterogeneous cardiomyopathy with SNPs associated with LGALS3, AGCT, SLC25A13, HRG, APOB, SOD3, SYNM, and TLN2." (PMID 34572079, 2021). "Recently, mutations in synemin (SYNM gene, OMIM *606087) have been linked to cardiomyopathy." (PMID 33923914, 2021).
dilated cardiomyopathy (2 papers, 2020 to 2021). Cardiomyopathy which is characterized by dilation and contractile dysfunction of the left and right ventricles. "Recent clinical reports have shown that synemin mutations led to multiple cases of dilated cardiomyopathy." (PMID 32258037, 2020). "The resulting phenotype in old mice, a mixture of changes associated with both hypertrophic and dilated cardiomyopathy, illustrates the important yet complex role of synemin in the heart." (PMID 32258037, 2020). "Mutations in synemin have been associated to dilated cardiomyopathy." (PMID 33923914, 2021). "To date, four mutations in the synemin gene (SYNM, GenBank reference sequences NM_145728 and NM_015286) have been linked to dilated cardiomyopathy." (PMID 32258037, 2020). "Recently, synemin mutations (SYNM gene, OMIM *606087) have been linked to dilated cardiomyopathy (DCM), while skeletal muscle disease has never been described." (PMID 33923914, 2021).
glioma (2 papers, 2012 to 2019). A benign or malignant brain and spinal cord tumor that arises from glial cells (astrocytes, oligodendrocytes, ependymal cells). "Nevertheless, precise mechanisms of synemin actions in glioma are missing." (PMID 31003495, 2019). "Glioma cells may express the intermediate filaments vimentin, GFAP, nestin, synemin, and α-internexin." (PMID 31003495, 2019).
hepatocellular carcinoma (2 papers, 2020 to 2022). A malignant tumor that arises from hepatocytes. "Interestingly, in human hepatocellular carcinomas, a down-regulation of synemin fails to alter the stability of the cytoskeleton, indicating the tissue specificity and multifunctionality of synemin." (PMID 32605308, 2020).
colorectal cancer (1 paper, 2022). A primary or metastatic malignant neoplasm that affects the colon or rectum. "SYNM is an important gene protein that is downregulated during the carcinogenesis of colorectal cancer." (PMID 36404510, 2022).
endothelial dysfunction (1 paper, 2017). In vascular diseases, endothelial dysfunction is a systemic pathological state of the endothelium (the inner lining of blood vessels) and can be broadly defined as an imbalance between vasodilating and vasoconstricting substances produced by (or acting on) the endothelium. "Knockout of vimentin, but not of synemin, resulted in increased carotid stiffness and contractility and endothelial dysfunction, independently of blood pressure and the collagen/elastin ratio." (PMID 28912461, 2017).
head and neck squamous cell carcinoma (1 paper, 2020). A squamous cell carcinoma that arises from any of the following anatomic sites: lip and oral cavity, nasal cavity, paranasal sinuses, pharynx, larynx, and salivary glands. "Here, using a high-throughput RNAi-based screen in three-dimensionally-grown cell cultures of head and neck squamous cell carcinoma (HNSCC), we identified novel focal adhesion proteins controlling DNA repair, including the intermediate filament protein, synemin." (PMID 32605308, 2020).
lung carcinoma (1 paper, 2022). "The experimental results show that CEP55, NMU, CAV1, TBX3, FBLN1and SYNM have significantly different expression in lung cancer." (PMID 36404510, 2022).
thyroid cancer (1 paper, 2022). "In addition, the DNA methylation of the SYNM gene can regulate the transcription level in thyroid cancer." (PMID 36404510, 2022).
type 2 diabetes (1 paper, 2023). "For four of the top six CpGs previously identified in a meta-EWAS of type 2 diabetes that had bidirectional 2SMR data (CpGs in TXNIP, HDAC4, SYNM and ABCG1), the observational and causal effects were consistent only at HDAC4 (cg00144180)." (PMID 37202507, 2023).
cancer (11 papers, 2020 to 2025). A tumor composed of atypical neoplastic, often pleomorphic cells that invade other tissues. "PNLDC1, SLC5A1, and SYNM were then identified as hub genes that were associated with both platinum response status and prognosis, which was further validated by the Fudan University Shanghai cancer center (FUSCC) cohort." (PMID 35361267, 2022). "The hub genes ATP6AP2, ACTR1A, SYNM, ZMYND8, CAMTA1, SLC39A3, and DHCR24, are associated with cancer development and progression." (PMID 39757707, 2025). "As expected, most up-regulated proteins are related to cancer genes, with seven of them known to be enhanced in PCa (SYNM, DES, MYH11, TAGLN, CNN1, LMOD1, and PGM5)." (PMID 38052461, 2024). "For example, MAD2L2 and LRRC61 are risk factors in most cancers, while PFKFB3, ESAM, SYNM, and LRFN5 act as protective factors in most cancers." (PMID 38124743, 2023). "According to our results, higher levels of SYNM and CNNN1 were found to be positively associated with increased IC50 values of cancer therapy drugs, whereas the expression of OGN and C2orf40 exhibited an opposite correlation." (PMID 37605453, 2023). "Our data generated in more physiological 3D cancer cell culture models suggest c-Abl as further key determinant of radioresistance downstream of synemin." (PMID 33019757, 2020). "To gain deeper insight into the functions of focal adhesion proteins (FAP) in the therapy resistance of HNSCC cancer cells, we established a 3D high-throughput RNAi-based screen (3DHT-RNAi-S) and identified a previously uncharacterized function of the IF protein, synemin." (PMID 32605308, 2020). "For the remaining genes in this set, namely TCEAL2, SYNM, and DES, direct validation of their functional roles in different cancers remains to be done." (PMID 41439026, 2025).
tumor (7 papers, 2017 to 2025). "Synemin is an intermediate filament–related protein playing a role in the formation of hepatocellular carcinoma, and changes in its expression level may lead to tumor cell polymorphisms." (PMID 32670437, 2020). "Among them, BNC2, SYNM, and TCF21 target genes were detected in all tumor locations, and three targets (GRIK2, KLHL14, and MS4A2) were shared by R-CRC and L-CRC but not by RC." (PMID 37987361, 2023). "Four genes (EPHA7, SOCS2, SYNM, WNK2) are tumor suppressor genes whose hypermethylation is a common mechanism of downregulation." (PMID 28927421, 2017).
myopathies (2 papers, 2018 to 2021). "The phenotype of the desmin-null mice and those of the mdx and synemin-null mice, studied earlier, are consistent with the severity of the myopathies seen in these animals." (PMID 34489727, 2021).
heart disease (1 paper, 2020). "Recently, synemin mutations have been found in association with disease, in particular, heart disease." (PMID 32258037, 2020). "Further evidence of the functional importance of synemin includes reports of mutations in synemin leading to heart disease and a rare condition that affects multiple tissues including bone and heart (ulnar-mammary-like syndrome)." (PMID 32258037, 2020). "Therefore, a loss of synemin resulted in heart disease in old mice, even young mice displayed reduced left ventricular contractility." (PMID 32258037, 2020).
SYNM also shares sentences with these, for which no sentence is quoted: asthma (1 paper); brain injuries (1); cervix squamous cell carcinomas (1); Desminopathy (1); diabetes (1); head and neck cancer (1); left ventricular hypertrophy (1); lung squamous cell carcinomas (1); metastatic tumors (1); pancreatic cancer (1); squamous cell carcinoma (1).